ARG1 (arginase 1)
Diseases named in the same sentence as ARG1 in open-access papers (continued):
Sharing a sentence is not in itself a finding about the gene and the disease.
neuropathy (2 papers, 2022). A disorder affecting the nervous system that manifests with pain, tingling, numbness, and/or muscle weakness. "To investigate the activation state of macrophages in the Nmnat2V98M/R232Q neuropathy, we profiled expression of both iNOS and Arg1 in activated macrophages throughout disease." (PMID 36287209, 2022). "Given the preponderance of Arg1+ activated nerve macrophages, i.e., the canonical antiinflammatory macrophage phenotype, we predicted that macrophage depletion would worsen the neuropathy of Nmnat2V98M/R232Q mice." (PMID 36287209, 2022). "Therefore, upregulation of iNOS and downregulation of ARG-1 promote deteriorative secondary neuropathy and more intense neuroinflammation in the injured cord tissues post-SCI." (PMID 36238284, 2022).
oral squamous cell carcinoma (2 papers, 2021 to 2024). "Compared with high endogenous expression of ARG1 in Huh7 control cells, we show that ARG1 was not detectable in oral squamous cell carcinoma (SCC9, SCC25 and Cal27) or noncancer keratinocyte (HaCaT) control cells." (PMID 34885177, 2021).
osteomyelitis (2 papers, 2020 to 2026). An acute or chronic inflammation of the bone and its structures due to infection with pyogenic bacteria. "We identified that significant infiltration of Arg1+Sdc4+, Cxcl1+Ccl4+, and Mif+Cd63+ macrophages may affect osteomyelitis through the Ccl3-Ccr1 and Cxcl2-Cxcr2 signaling pathways." (PMID 41836400, 2026).
osteosarcoma (2 papers, 2017 to 2020). A usually aggressive malignant bone-forming mesenchymal neoplasm, predominantly affecting adolescents and young adults. "In osteosarcoma, both ARG1 and ARG2 catabolic enzymes were moderately expressed." (PMID 28969007, 2017). "It was reported that M2-like macrophage marker molecules, including CD206, Arg-1, and Ym-1, were significantly upregulated in the osteosarcoma tissues compared with non-tumor tissues." (PMID 33363016, 2020).
Peritoneal Fibrosis (2 papers, 2013 to 2022). Disorder characterized by a wide range of structural changes in PERITONEUM, resulting from fibrogenic or inflammatory processes. "Our results revealed that peritoneal thickness, Col-I, fibronectin, CD206, TGF-β, Ym-1 and Arg-1 were upregulated in the peritoneal fibrosis mice model, and all of these indexes were downregulated in those treated with LC." (PMID 23685870, 2013). "In addition, the staining colocalized HDAC6 and Arginase-1 in IL-4-stimulated Raw264.7 cells, which provided support that HDAC6 might promote peritoneal fibrosis via manipulating M2 polarization." (PMID 35784347, 2022).
preeclampsia (2 papers, 2022 to 2025). Preeclampsia is a hypertensive disorder of pregnancy that is characterized by new-onset hypertension with proteinuria presenting after 20 weeks of gestation, and depending on mild or severe forms may initially present with severe headache, visual disturbances, and hyperreflexia. "Preeclampsia (PE) patients exhibit significantly lower serum arginase-1 (Arg-1) levels than healthy controls." (PMID 40881171, 2025). "Further investigation on molecular markers were consistent with our in vitro findings, Arg-1 level was decreased and iNOS level was increased in placenta tissues from the preeclampsia group, indicating the inhibited M2 polarization of macrophages." (PMID 36153499, 2022). "In addition, placenta samples of preeclampsia patients showed decreased levels of Arg-1 (a marker of M2 macrophage subtype) and increased levels of iNOS (a marker of M1 macrophage subtype)." (PMID 36153499, 2022). "Correlation analysis indicated a positive correlation between levels of LINC00240 and Arg-1, and a negative correlation between levels of LINC00240 and iNOS in placenta samples of preeclampsia patients." (PMID 36153499, 2022).
prostatic adenocarcinoma (2 papers, 2012 to 2017). "In a model of human prostatic adenocarcinomas, only concomitant inhibition of arginase 1 and NOS2 reduces PNT production and recovers tumor-infiltrating lymphocyte antitumor responsiveness." (PMID 28223985, 2017).
Salmonella Infections (2 papers, 2021 to 2024). Infections with bacteria of the genus SALMONELLA. "In contrast to our Salmonella infection model, induction of Arg1 in L. major infection in BALB/c mice was driven by a strong Th2 response releasing IL-4 and IL-13 and not by the pathogen itself." (PMID 34359992, 2021). "In summary, we found a prominent induction of ARG1 in macrophages upon Salmonella infection and an opposite regulation of ARG1 by IL-4 and IFNγ." (PMID 34359992, 2021). "(C–E) RT-qPCR analysis of mRNAs encoding inflammatory cytokines (Tnfα, Il1β, and Il6), chemokines (Ccr2, Ccl2, Cxcl1, and Cxcl10) and macrophage biomarkers (Nos2 and Arg1) in BMDMs measured at the indicated times after Salmonella infection (multiplicity of infection [MOI] = 1) (n = 5)." (PMID 39475776, 2024).
serous ovarian carcinoma (2 papers, 2019 to 2023). "Overall, these observations do not provide an indication for enhanced ARG1, iNOS or GLS1 enzyme activity in high-grade serous ovarian cancer patients." (PMID 36765849, 2023).
silicosis (2 papers, 2022 to 2024). Silicosis is a respiratory disease caused by breathing in (inhaling) silica dust. "To verify if this was also the case in the silicosis mouse model, we stained iNOS and Arg1, specific markers of M1 and M2, respectively." (PMID 35401236, 2022). "A previous study by our group on a rat silicosis model showed that BIC suppresses the aggregation and activation of macrophages through down-regulation of Arg1 and iNOS." (PMID 39060930, 2024).
status epilepticus (2 papers, 2020 to 2021). Status epilepticus is defined as a continuous seizure lasting more than 30 min, or two or more seizures without full recovery of consciousness between any of them. "It not only reduced the upregulation of pro-inflammatory markers [inducible nitric oxide synthase (iNOS) and cyclooxygenase 2 (COX2)] in status epilepticus mice, but also increased the levels of microglial anti-inflammatory marker arginase-1 (Arg-1)." (PMID 34924959, 2021).
steatosis (2 papers, 2022 to 2024). Increased lipid within the cytoplasm of cells. "Mechanistically, liver damage and steatosis caused by autophagy deficiency in these mice promotes the release of arginase 1 (ARG1) into the bloodstream, which catalyzes the degradation of arginine into ornithine and subsequently decreases circulating arginine levels." (PMID 35646940, 2022).
thalassemia (2 papers, 2022). An inherited blood disorder characterized by a decreased synthesis of one of the polypeptide chains that form hemoglobin. "It is known that arginine metabolism is dysregulated in thalassemia, while increased arginase-1 expression (currently observed in β+ versus β++) and activity, in parallel with low l-arginine levels have been linked to oxidative stress and hemolysis." (PMID 35755442, 2022).
type 1 diabetic (2 papers, 2017 to 2021). "Cutaneous wound closure, CD68- and arginase-1 (Arg-1)-expressing macrophages, and cytokine mRNA expression were examined in non-diabetic and streptozotocin-induced type 1 diabetic mice at different time points after injury." (PMID 28542434, 2017).
urothelial carcinoma (2 papers, 2021 to 2025). A malignant neoplasm derived from the transitional epithelium of the urinary tract (urinary bladder, ureter, urethra, or renal pelvis). "In some of these cases, arginase-1 positivity occurred in areas of squamous differentiation (urothelial carcinoma, pleomorphic adenoma) or in the keratinizing squamous epithelium of a testicular teratoma." (PMID 34943588, 2021).
Acidosis (1 paper, 2020). Abnormal acid accumulation or depletion of base. "Acidosis decreased the gene expression of the pro-inflammatory markers Nos2, Ccl2, and IL-6 in IFN-γ/lipopolysaccharide-polarized macrophages, and it increased the expression of anti-inflammatory markers CD206 and Arg1 in IL-4-polarized macrophages." (PMID 32823915, 2020).
acute kidney injury (1 paper, 2024). Sudden and sustained deterioration of the kidney function characterized by decreased glomerular filtration rate, increased serum creatinine or oliguria. "The iNOS+ M1-like macrophages infiltrated the kidney in the first 48 hours after acute kidney injury, while Arg-1+ M2-like macrophages dominated in the later time." (PMID 39494325, 2024).
acute respiratory distress syndrome (1 paper, 2023). Progressive and life-threatening pulmonary distress in the absence of an underlying pulmonary condition, usually following major trauma or surgery. "In addition, gMDSC express high levels of arginase-1 and neutrophil degranulation markers, many of which contribute to a transcriptomic phenotype corresponding to plasma protein hyperinflammation during acute respiratory distress syndrome (ARDS)." (PMID 36941659, 2023).
African trypanosomiasis (1 paper, 2019). "This identifies arginase-1 as a potential target in African trypanosomiasis when considering treatment and vaccination strategies." (PMID 31824512, 2019).
alcoholic liver cirrhosis (1 paper, 2022). A disorder of the liver characterized by the presence of fibrotic scar tissue instead of healthy liver tissue. "In alcoholic liver cirrhosis patients, level of plasma ARG-1 secreted by MDSCs were correlated with INR." (PMID 36263056, 2022).
amino acid disorders (1 paper, 2020). "Expanded NBS for amino acid disorders using tandem mass spectrometry includes the possibility of determining arginine levels, thus allowing for the detection of increased risk for arginase-1 deficiency." (PMID 32872442, 2020).
ankylosing spondylitis (1 paper, 2024). An autoimmune chronic inflammatory disorder characterized by inflammation in the vertebral joints of the spine and sacroiliac joints. "Stat3/Arg-1 signaling was reported to play an important role in the expansion and activation of M-MDSC cells in patients with Ankylosing Spondylitis (AS)." (PMID 39013845, 2024).
autoimmune uveitis (1 paper, 2025). An autoimmune form of uveitis (disease). "In the context of autoimmune uveitis, a higher abundance of ARG1 has been associated with infiltrating myeloid cells, especially macrophages, in the uveitic retina of rodents with EAU." (PMID 40001591, 2025).
bladder tumors (1 paper, 2021). "The MDSCs present in bladder tumors have been shown to express high levels of immunosuppressive molecules such as Arginase 1, inducible nitric oxide synthases (iNOS) and PD-L1 and directly suppress T-cell proliferation reflecting their phenotype in the peripheral blood." (PMID 34777336, 2021).
bronchopneumonia (1 paper, 2021). Acute inflammation of the walls of the terminal bronchioles that spreads into the peribronchial alveoli and alveolar ducts. "Arg-1 immunolabelling was detected mainly in the cytoplasm of PAMs placed inside or surrounding bronchopneumonia foci, but also in PIMs and interstitial macrophages in a lesser extent." (PMID 33482914, 2021).
bruxism (1 paper, 2025). Excessive clenching of the jaw and grinding of the teeth. "The findings of the study showed decreased levels of arginase 1 and ceruloplasmin, suggesting an association between tooth grinding and enzymes involved in the nitric oxide pathway, irrespective of bruxism severity." (PMID 40990027, 2025). "Results for Arg1 and ceruloplasmin in bruxers and nonbruxers, differentiated based on bruxism severity." (PMID 40990027, 2025).
cataract (1 paper, 2023). Partial or complete opacity of the crystalline lens of one or both eyes that decreases visual acuity and eventually results in blindness. "The mechanisms of ARG1 in epithelial-to-mesenchymal transition (EMT)-associated cataracts were studied herein." (PMID 37723490, 2023). "To elucidate the regulatory roles of ARG1 in the development of EMT-associated cataracts, we established a mouse anterior lens capsule injury model, a TGF-β2-induced EMT model and a mouse lens culture model and used human anterior capsule membrane samples." (PMID 37723490, 2023). "We investigated the specific molecular mechanisms by which ARG1 regulates EMT in fibrotic cataracts." (PMID 37723490, 2023). "We show for the first time that ARG1 can regulate EMT in fibrotic cataracts." (PMID 37723490, 2023). "We believe that ARG1 promotes the production of collagen 1A1 by directly activating the arginase pathway and leads to lens fibrosis by reducing NO production and increasing superoxide levels, providing a new mechanism for the prevention and treatment of fibrotic cataracts." (PMID 37723490, 2023).
cerebral malaria (1 paper, 2025). A sequestration of Plasmodium falciparum in the brain, which can cause coma and/or seizures. "MMP8, IL1R2, and ARG1 transcription is higher across cerebral malaria, severe malarial anemia, and concurrent cerebral malaria and severe malarial anemia, indicating a shared inflammatory signature." (PMID 40383794, 2025). "L-arginine metabolites are decreased in cerebral malaria, which coupled with increased ARG1 transcription suggests a putative mechanism impairing cerebral vasodilation." (PMID 40383794, 2025).
chondrosarcoma (1 paper, 2023). A malignant cartilaginous matrix-producing mesenchymal neoplasm arising from the bone and soft tissue. "Further analysis revealed that M2 macrophages polarized by exosomes expressed arginase-1 and feedback to chondrosarcoma cells to promote migration." (PMID 37993261, 2023). "Polarization of M2 macrophages leads to transcription of genes associated with the immunosuppressive macrophage phenotype in chondrosarcoma, including immunosuppressive markers such as arginase-1, TGF-β, and IL-10, as well as chemokines." (PMID 37993261, 2023).
chronic GVHD (1 paper, 2015). "Since neutrophils cleave chemokines, can produce reactive oxygen and nitrogen species and secrete Arginase-1, they are capable of influencing T cell activation and have thereby the potential to contribute to the pathogenesis and maintenance of chronic GVHD as well." (PMID 26241482, 2015).
chronic hepatitis (1 paper, 2022). An active inflammatory process affecting the liver for more than six months. "MDSCs in this inflammatory environment produce Arg-1 and increased Arg-1+ cells in the liver were closely associated with tissue pathology in patients with chronic hepatitis." (PMID 35092727, 2022).
chronic lung disease (1 paper, 2021). According to the definitions of the American and British Thoracic Societies, including pulmonary functional tests, X-rays, and CT scans for items such as fibrosis, bronchiectasis, bullae, emphysema, nodular or lymphomatous abnormalities. "We analyzed the expression of selected genes associated with AM plasticity (Ccl22, Ccl17, Mmp12, and Arg1) and inflammation in chronic lung diseases (Il1a and Il1b)." (PMID 34764283, 2021).
chronic lymphocytic leukemia (1 paper, 2024). "Duvelisib is an FDA-approved PI3K γ/delta inhibitor for chronic lymphocytic leukemia (CLL) that has been shown to decrease MDSC induction of Arginase 1 (Arg1) and nitric oxide synthase 2 (NOS2) transcripts and enhance immunotherapy in preclinical models when given at low doses." (PMID 38474232, 2024).
chronic myelomonocytic leukaemia (1 paper, 2022). "Interestingly, high Arg1 expression has been associated with myelodysplastic syndromes (MDS) and chronic myelomonocytic leukaemia (CMML) in humans, and both of these diseases are commonly associated with AHN in patients with systemic mastocytosis." (PMID 35393954, 2022).
chronic rhinosinusitis (1 paper, 2019). Chronic form of sinusitis. "ARG1 expression levels were globally low in the group of patients with chronic rhinosinusitis and in the control group, which is why these were not considered for statistical analysis." (PMID 31683763, 2019).
clear cell carcinoma (1 paper, 2025). "Immunostaining of the tumor revealed hepatocyte, arginase 1, CK20, CD10, CA9, and TFE3 negativity, along with AE1/AE3 and CK7 positivity, leading to the diagnosis of clear cell carcinoma of the liver." (PMID 41018392, 2025).
Coccidioides infection (1 paper, 2025). "In response to Coccidioides infection, Spp1+ macrophages express high levels of pro-inflammatory (Nos2, Tgfb1, Il1β, and Il6) and fibrotic/wound healing associated genes (Inhba, Spp1, Arg1, Pdgfb, and Fn1)." (PMID 40704794, 2025).
dermatitis (1 paper, 2020). An inflammatory process affecting the skin. "Further studies could provide novel insights into the functional roles of CD163 and Arg1 during oxazolone-induced dermatitis." (PMID 33122966, 2020).
diabetic foot (1 paper, 2019). A diabetic foot is a foot that exhibits any pathology that results directly from diabetes mellitus or any long-term (or "chronic") complication of diabetes mellitus. "Correspondingly, the upregulated ARG1 expression has been reported in patients with diabetic foot and venous ulcers as well as in chronic wounds in recessive dystrophic epidermolysis bullosa." (PMID 31396302, 2019).
endometrioid adenocarcinoma (1 paper, 2018). An adenocarcinoma characterized by the presence of malignant glandular epithelial cells resembling endometrial cells. "Histologically, the tumor was an endometrioid adenocarcinoma with sarcomatous element and a hepatoid component, the latter was immunohistochemically positive for alpha-fetoprotein, HepPar-1, and arginase-1." (PMID 29992073, 2018).
falciparum malaria (1 paper, 2016). "We show here that children with falciparum malaria have significantly increased levels of PBMC arginase 1 mRNA and protein, elevated plasma arginase activity, decreased PBMC NOS2 mRNA, and dramatically increased plasma levels of IL-10." (PMID 27385484, 2016). "We note that Tanzanian children with falciparum malaria have markedly increased PBMC arginase 1 and IL-10, reduced PBMC NOS2 and plasma arginine, and monocytes expressing markers of alternative activation (M2-like monocytes)." (PMID 27385484, 2016). "Compared to control children (n = 106), children with moderately severe (n = 77) and severe falciparum malaria (n = 129) had significantly higher mononuclear cell arginase 1 mRNA, protein, and enzyme activity; lower NOS2 mRNA; lower plasma arginine; and higher plasma IL-10, IL-13, and IL-4." (PMID 27385484, 2016). "Since M2 cells express very low NOS2/NO and produce high levels of arginase 1, an enzyme that depletes the NOS substrate arginine, we sought to characterize monocytes from children with falciparum malaria." (PMID 27385484, 2016).
filariasis (1 paper, 2015). "Indeed, in patients with filariasis, an increased expression of arginase-1 in M2 monocytes was demonstrated." (PMID 26496711, 2015).
gastric adenocarcinoma (1 paper, 2020). "In this study, we first analyzed by flow cytometry the phenotype and the ARG1 expression level in MDSCs from peripheral blood and cancerous tissue of gastric adenocarcinoma (GAC) patients." (PMID 32415175, 2020). "In our study, flow cytometric analysis of circulating MDSCs from 20 gastric adenocarcinoma (GAC) patients found that ≥80% ARG1-expressing MDSCs were mainly early-stage MDSCs (HLA-DR−CD33+CD14−CD15−MDSCs)." (PMID 32415175, 2020).
glaucoma (1 paper, 2023). Increased pressure in the eyeball due to obstruction of the outflow of aqueous humor. "Analysis of a circRNA–miRNA–mRNA interaction network found that hsa_circ_0000745 and DEcircRNAs could potentially form a regulatory relationship with ARG1 and NEAT1 through the miRNAs, which may affect immune cell function, thereby promoting the development of glaucoma." (PMID 37805546, 2023).
gout (1 paper, 2020). A condition characterized by painful swelling of the joints, which is caused by deposition of urate crystals. "Results showed that P47phox was significantly increased in gout-PMN-MDSCs compared to control-PMN-MDSCs, whereas the mRNA levels of arg-1 and NOS2 were not significantly affected." (PMID 33154749, 2020).